NF1 (neurofibromin 1)
Diseases named in the same sentence as NF1 in open-access papers (continued):
Sharing a sentence is not in itself a finding about the gene and the disease.
glioblastoma (continued). "Taken together, our data support a model in which heterogeneity underlies clinical outcomes and MEK inhibitor response within NF1-mutant glioblastomas." (PMID 40985888, 2025). "Although our study focused on NF1 loss leading to Ras activation, RTKs, such as PDGFRA and EGFR, which are recurrently mutated in glioblastoma, can also activate Ras signaling through Ras GEFs such as SOS1." (PMID 40985888, 2025). "CPH analysis of clinical variables associated with OS in the NF1-mutant, IDH wild-type glioblastoma cohort revealed age, KPS, multifocality, adjuvant radiation, adjuvant temozolomide, and tumor-treating fields as being associated with OS (P < 0.1)." (PMID 40985888, 2025). "Single-nucleus RNA sequencing (snRNA-Seq) of patient glioblastomas (n = 9) demonstrated that MES-like cells within NF1-mutant tumors exhibited increased MEK activation." (PMID 40985888, 2025). "The classification was further refined by separating the rare glioblastoma cases with MMR deficiency into a G3/MMR molecular subgroup, a spin-off of the G3/NF1 subgroup, since RAS activation appears to be dominant in the MMR tumors, as well." (PMID 38254850, 2024). "No tumors demonstrated EGFR amplification, MET amplification, CDK4 amplification, MDM2 or MDM4 amplification, PTEN homozygous deletion, or NF1 homozygous deletion that are frequent oncogenic events in conventional IDH-wildtype glioblastomas." (PMID 38079020, 2023). "In glioblastoma cells, PKCε has been shown to phosphorylate NF1 at Ser2808, thereby altering its nuclear distribution." (PMID 37355626, 2023). "The GFAP-TVA-dependent glial cell-specific Nf1 (neurofibromin) inactivation, along with K-RasG12V expression, triggers the growth of the most aggressive glioblastoma subtype (MES), exhibiting mesenchymal features." (PMID 37176013, 2023). "On the contrary, the mutation of PTEN, EGFR, TTN, NF1, SPTA1 and RB1, which occurred frequently in glioblastoma, were more frequently in PVT1 higher group." (PMID 37202742, 2023). "However, EGFR, PTEN and NF1, the mutations that were common in glioblastoma (GBM), were more frequent in C2 than C1." (PMID 38053842, 2023). "In glioblastoma, loss of several factors, including PTEN, NF1 and KLF6, as well as increased activity/expression of others, including PIN1, MLK4 and microRNA-30e, have all been shown to contribute to NF-κB activation." (PMID 35922651, 2022). "We identified a second glioblastoma case from the UCSF500 cohort with TERTp duplication, gain of chromosome 7, loss of chromosome 10 and homozygous deletion of CDKN2A as well as an NF1 frameshift mutation." (PMID 36114166, 2022). "For glioblastoma cells, it has been shown that NF1 incompetence led to a decreased cancer cell homogeneity, enhanced NF1 expression led to diminished microglia activity and vice versa, and NF1 deactivation results in increased macrophage activation." (PMID 34687436, 2022). "While IDH wild-type LGG closely resembles glioblastoma (GBM) in both molecular signatures and clinical behavior, often including PTEN, EGFR and NF1 mutations." (PMID 36589241, 2022). "The gene mutation pattern of the high-CCNScore group was similar with glioblastoma, including EGFR, PTEN, and NF1 mutation frequently." (PMID 36589241, 2022). "Comparing with the patients without surgery resection, we thought the standard treatment regimen was still the most effective for adult patients with supratentorial glioblastoma and NF1." (PMID 33787635, 2021). "Tumor infiltrating lymphocytes, or TILs, are often enriched in glioblastoma (GBM) with a mesenchymal gene expression signature and are strongly associated with mutations in NF1 and RB1." (PMID 34496929, 2021).
glioblastoma (continued). "In glioblastoma cells, KBTBD7 destabilized NF1 tumor suppressor, suggesting that it has an oncogenic role in the pathogenesis of glioblastoma." (PMID 33990333, 2021). "A recent Phase I/II study of DSF and Cu++ with concurrent radiation therapy and TMZ for newly diagnosed glioblastoma demonstrated promising preliminary efficacy for a subset of tumors with IDH1, BRAF, and NF1 mutations." (PMID 34731160, 2021). "For example, CUL3-KBTBD7 has been shown to destabilize neurofibromin 1 (NF1) in glioblastoma cells, making it a potential therapeutic target for glioblastoma." (PMID 33990333, 2021). "Adding further complexity, it has been reported that PKC-α phosphorylates NF1 in response to growth factors, addressing this protein for proteasomal degradation in murine embryonic fibroblasts and glioblastoma cells." (PMID 33096593, 2020). "Amongst these, IDH, PDGFR, and PIK3CA alterations characterize proneural glioblastoma, EGFR amplification occurs in classical glioblastoma, and NF1, PTEN, and NFκB mutations predominate in mesenchymal subtypes." (PMID 33396284, 2020). "In glioblastoma multiforme (GBM), NF1 is one of the most frequently mutated or deleted genes." (PMID 25026295, 2014). "Glioblastoma datasets from The Cancer Genome Atlas were analyzed for alterations in EGFR, PDGFRA and NF1 and the possible association of mutations in these genes with transcriptomally-defined subclasses." (PMID 19915670, 2009). "Consistent with prior work demonstrating MEK inhibitor efficacy selectively against NF1-mutant glioblastoma, in vitro cell viability analysis showed that NF1-mutant glioblastoma cells were significantly more sensitive to selumetinib compared with NF1 wild-type glioblastoma cells." (PMID 40985888, 2025). "Although MES-like cells from both NF1-mutant and NF1 wild-type glioblastomas showed increased expression of the MEK activation signature, MES-like cells in NF1-mutant glioblastomas showed significantly increased MEK activation compared with MES-like cells in NF1 wild-type tumors." (PMID 40985888, 2025). "We hypothesize that NF1 alteration serves as a predictive biomarker for MEK-inhibition targeting migratory growth in newly diagnosed glioblastoma patients." (PMID 40575417, 2025). "NF1-mutant glioblastomas had significantly fewer neurons (C8), but no other nontumor populations existed in significantly different proportions between NF1-mutant and NF1 wild-type glioblastomas." (PMID 40985888, 2025). "Yet, larger scale studies have shown no survival differences based on NF1 mutation status in glioblastoma." (PMID 41212363, 2025). "NF1 alteration (HR: 1.28), PIK3CA/3R1 alteration (HR: 1.25), CDKN2A/B loss (homozygous or heterozygous, HR: 1.21), and increasing age (HR: 1.03) negatively impacted survival for glioblastoma." (PMID 39164213, 2025). "SHOC2 perturbation to block downstream Ras outputs may thus also be useful in NF1 intact tumors as observed in other systems, and further work is needed to formally test this possibility in glioblastoma." (PMID 40985888, 2025). "EGFR, NF1, and PDGFRA mutations are more frequent in glioblastoma." (PMID 40564017, 2025).
glioblastoma (continued). "Our observations regarding MEK activation in MES-like cells from NF1-mutant glioblastomas may provide the initial steps in defining a molecular biomarker for MEK inhibitor response in NF1-mutant glioblastoma." (PMID 40985888, 2025). "Furthermore, expression of several genes associated with glioblastoma (STAT3, PDGFRA, MET, and NF1) and neuroblastoma (GATA3, ISL1, LMO1, and LIN28B) progression was downregulated at the transcriptional level in differentiated cells." (PMID 39859209, 2025). "Cox proportional hazards (CPH) analysis of recurrently comutated genes revealed CDKN2A/B homozygous loss was associated with worse OS in NF1-mutant but not NF1 wild-type glioblastomas." (PMID 40985888, 2025). "The case underscores the intricate interplay between genetic predisposition, tumor biology, and treatment response, emphasizing the imperative for further research to comprehend the underlying mechanisms driving the occurrence and aggressive nature of glioblastoma in the context of NF1." (PMID 39211378, 2024). "To identify whether pathogenic alterations in NF1 are associated with changes in mRNA or protein expression, we interrogated the TCGA and CPTAC glioblastoma cohorts." (PMID 39472976, 2024). "NF1 loss may also be a harbinger of exploitable vulnerabilities in IDH-wildtype glioblastoma (GBM)." (PMID 39472976, 2024). "Limited data exist on glioblastomas in individuals with NF1, with few cases reported." (PMID 39211378, 2024). "Most likely, age, coupled to a higher number of female patients contributing tumors to the G3/NF1 subgroup, explains the balanced distribution of the major subgroups in the Validation cohort, and suggests age and sex dependence for glioblastoma molecular profiles." (PMID 38254850, 2024). "In our institutional cohort of 542 glioblastomas, we observed that neither truncating NF1 alterations in the entire cohort nor NF1 genomic loss in the TMA cohort alone were significantly associated with decreased overall survival." (PMID 39472976, 2024). "It is unclear how NF1 could provide a protective prognostic effect in CDKN2Aint patients, but this dichotomous impact of NF1 on survival in CDKN2A stratified patients suggests that CDKN2A may significantly modulate NF1 activity in IDHwt glioblastoma patients." (PMID 36380219, 2022). "Conversely, mesenchymal subtype glioblastomas were characterized by high expression of chitinase 3 like 1 (CHI3L1) and tyrosine-protein kinase Met (MET), a high frequency of neurofibromin 1 (NF1) mutation/deletion, and low NF1 gene expression." (PMID 36591531, 2022). "Summary of adult NF1 patients with supratentorial glioblastoma." (PMID 33787635, 2021). "We reported a rare case of glioblastoma in a 51-year-old woman with NF1." (PMID 33787635, 2021). "Glioblastoma cases belonging to the mesenchymal subtype are frequently characterized by the presence of focal hemizygous deletions at 17q11.2 region encompassing the NF1 gene." (PMID 33324155, 2020).
glioblastoma (continued). "Mesenchymal glioblastomas maintain a high expression of CH13L1, MET, and genes associated with tumour necrosis factor and nuclear factor-κB pathways, along with mutations and deletions of NF1." (PMID 29189740, 2017). "Data from mouse models support the importance of NF1 as a glioblastoma suppressor gene." (PMID 25026295, 2014). "Taken together, these data suggest that while MES-like cells are enriched within NF1-mutant glioblastomas, marked inter- and intratumor heterogeneity exists, and MES-like cells harbor distinct transcriptional signatures enriched for Ras/RAF/MEK activation downstream of NF1 mutation." (PMID 40985888, 2025). "Finally, future preclinical studies and clinical trials aimed at complementing MEK inhibitors with alternative modalities, such as radiation, immunotherapy, or targeted agents against comutated genes such as CDKN2A/B, will be critical to achieve durable responses in NF1-mutant glioblastomas." (PMID 40985888, 2025). "A genome-wide CRISPR interference (CRISPRi) screen to identify potential targets that synergize with MEK inhibition in NF1-mutant glioblastoma (GBM) cells has recently been reported." (PMID 41294711, 2025). "In one recent HTS, patient-derived glioblastoma (GBM) spheroid models were used to identify drivers of GBM progression and therapeutic targets relevant to both NF1-mutant and NF1-WT tumors." (PMID 41294711, 2025). "The patients from this subgroup may benefit from immune checkpoint inhibitors, similarly to pediatric patients with glioblastoma in the context of MMR deficiency, while patients from G3/NF1 and G4/RAF subgroups may respond to targeted therapy with RAF and MEK inhibitors." (PMID 38254850, 2024). "Mutual exclusivity of NF1 and EGFR alterations in IDH-wildtype glioblastoma was further substantiated using two publicly available resources, TCGA and CPTAC, totaling 368 genomically-characterized glioblastomas after excluding samples with pathogenic IDH1/2 alterations." (PMID 39472976, 2024). "While the current study did not assess NF1 mRNA for correlation, this may indicate a subset of glioblastoma is inactivating NF1 post-transcriptionally through mechanisms such as proteasomal degradation or post-transcriptional silencing, or through other negative feedback mechanisms." (PMID 39472976, 2024). "Interestingly, NF1 is frequently inactivated in mesenchymal glioblastoma, IDH-wildtype and gliosarcoma, IDH-wildtype, suggesting that loss of NF1 may support glial-to-mesenchymal transition in general." (PMID 34967922, 2022). "The transition of pro-neural into mesenchymal glioblastoma stem cells is promoted by NFκB and YAP/TAZ signaling and can be triggered by hypoxia, reactive oxygen species, ionizing radiation, and genetic alterations such as the loss of the neurofibromin 1 (NF1) gene." (PMID 35803925, 2022). "Interestingly, EGFR-MAPK and PI3K-AKT-mTOR signaling is hyperactivated in glioblastoma by EGFR amplification, mutation of the MAPK pathway inhibitor Neurofibromin 1 and loss of the phosphatase and tensin homolog (PTEN) and is associated with resistance to radiation therapy in glioblastoma." (PMID 34771501, 2021).
glioblastoma (continued). "TCGA has grouped glioblastomas relying on proteomic data into three classes: one showing epidermal growth factor receptor (EGFR) mutations or amplifications, the second having ligand-driven platelet-derived growth factor (PDGF) activation, and the third with a loss of RAS regulator, NF1." (PMID 34884508, 2021). "The SUZ12 loss enhances colony growth of NF1-deficient (but not NF1 wild-type) glioblastoma cells." (PMID 34502310, 2021). "The neurofibromin-1 tumor suppressor gene (NF1) is altered in approximately 20% of sporadic glioblastoma (GBM) cases." (PMID 29643433, 2018). "The SUZ12 gene encodes a chromatin modifying protein, and its loss enhances colony growth of NF1-deficient (but not NF1 wild-type) glioblastoma cells, suggesting that reduced PRC2 levels might promote tumorigenesis." (PMID 28592921, 2017). "A TCGA analysis assessed levels of gene expression, CNAs and DNA methylation in a cohort of 206 glioblastoma tumour samples, with recurrent mutations in NF1, AKT3, PRK3R1 and PARK2 being identified, and with 14% (13/91) of samples found to contain at least one somatic NF1 mutation." (PMID 28637487, 2017). "Here, we found that several of the most frequently mutated genes in glioblastoma including: EGFR, PTEN, NF1, PIK3R1, RB1, PDGFRA and QKI possessed high 5 hmC levels across intronic regions and further loss of 5 hmC in tumours may reflect a loss of genome integrity." (PMID 27886174, 2016). "However, when the analysis was stratified by glioblastoma molecular subtype, high ABCG1 expression correlated with shorter overall survival only in the mesenchymal subgroup, a subtype characterized by NF1 gene mutation." (PMID 26981778, 2016). "These intragenic deletions included those targeting known tumour suppressors in glioblastoma such as NF1 (17q11.2, n = 2) and RB1 (13q14.2, n = 1), as well as putative novel GBM-associated genes including FAF1 (1p33, n = 2) and MTAP (9p21.3, n = 2)." (PMID 24548782, 2014). "In sum, our data support the existence of clinically significant intertumor and intratumor heterogeneity within NF1-mutant, IDH wild-type glioblastoma with distinct responses to the MEK inhibitor selumetinib." (PMID 40985888, 2025). "Here, we combine multimodal molecular and functional analyses to characterize clinically relevant subgroups and mechanisms of MEK inhibition response in NF1-mutant, IDH wild-type glioblastomas." (PMID 40985888, 2025). "To investigate the intratumor heterogeneity within somatic NF1-mutant, IDH wild-type glioblastomas, we next performed snRNA-Seq on a total of 21,959 nuclei from 9 patient glioblastomas." (PMID 40985888, 2025). "Well-known somatic drivers of glioblastoma (GBM) heterogeneity, including PDGFRA, IDH1, EGFR, and NF1, have altered how we treat patients, diagnose disease, and design clinical trials." (PMID 37252795, 2023).